PASD1 (PAS domain containing repressor 1)
Description:
Functions as a suppressor of the biological clock that drives the daily circadian rhythms of cells throughout the body. Acts as a nuclear repressor of the CLOCK-BMAL1 heterodimer-mediated transcriptional activation of the core clock components. Inhibits circadian clock function in cancer cells, when overexpressed.
Synonyms: CT63; CT64; OXTES1
Tractability: PROTAC: ubiquitination databases record sites on it.
Gene: Protein-coding gene on chromosome X (151,563,675 to 151,676,739, forward strand). Ensembl gene ENSG00000166049.
Subcellular location: Nucleus (Isoform 1); Nucleus (Isoform 2)
Subcellular location (Human Protein Atlas): Nuclear speckles
Gene Ontology:
Molecular function: DNA-binding transcription factor binding; protein binding; transcription regulator inhibitor activity; DNA-binding transcription factor activity, RNA polymerase II-specific; RNA polymerase II cis-regulatory region sequence-specific DNA binding
Biological process: negative regulation of circadian rhythm; negative regulation of DNA-templated transcription; circadian regulation of gene expression; regulation of transcription by RNA polymerase II; regulation of gene expression
Cellular component: Cry-Per complex; nuclear speck; nucleus; CLOCK-BMAL transcription complex
Homologues: Orthologues: chimpanzee PASD1 (96% identical), macaque PASD1 (87% identical), dog PASD1 (38% identical), rat Pasd1 (18% identical), mouse Pasd1 (17% identical), tropical clawed frog pasd1 (17% identical), zebrafish npas2 (16% identical), Drosophila melanogaster Clk (14% identical), Drosophila melanogaster Met (8% identical), Drosophila melanogaster gce (7% identical), Drosophila melanogaster tgo (6% identical), Caenorhabditis elegans aha-1 (5% identical). Paralogues in human: CLOCK (16% identical), NPAS2 (16% identical), ARNT (9% identical), ARNT2 (8% identical), BMAL1 (6% identical), BMAL2 (6% identical).
Diseases named in the same sentence as PASD1 in open-access papers:
PASD1 is named in the same sentence as 21 diseases in open-access papers, as found by Europe PMC text mining. Sharing a sentence is not in itself a finding about the gene and the disease. The quoted sentences say what the papers report.
glioma (4 papers, 2021 to 2023). A benign or malignant brain and spinal cord tumor that arises from glial cells (astrocytes, oligodendrocytes, ependymal cells). "SNPs rs12860832 and rs12849233 are found in the gene PAS domain containing repressor 1 (PASD1), which might serve as a new target for the prognosis and the future treatment of glioma." (PMID 36979477, 2023). "SNP rs12849233 is in PAS domain containing repressor 1 (PASD1), which might possibly serve as a new target for the prognosis and the future treatment of glioma." (PMID 35610583, 2022). "Besides CRC and polyps, PASD1 expressions have been reported in other cancers such as DLBCL and acute myeloid leukemia (AML) and glioma patients in which, all the studies involved cancer at an advanced stage." (PMID 37529004, 2022).
acute myeloid leukaemia (3 papers, 2015 to 2022). "For example, PASD1 expression was found in acute myeloid leukaemia (AML) and diffuse large B-cell lymphoma but has not been found in solid tumours such as basal cell carcinoma or ovarian cancer." (PMID 31970440, 2020). "Fourteen of the twenty-six acute myeloid leukaemia (AML) patients analysed had T cells that recognised tumour antigen epitopes, and eight of these recognised PASD1 epitopes." (PMID 26492414, 2015).
myeloid leukemia (3 papers, 2015 to 2018). A clonal proliferation of myeloid cells and their precursors in the bone marrow, peripheral blood, and spleen. "However PASD1 has been one of the most frequently expressed CTA in myeloid leukaemia while WT1 has been found to be one of the most frequently expressed LAAs." (PMID 26492414, 2015). "Our previous serological analysis of recombinant tumor cDNA expression libraries (SEREX) analysis of AML patient sera, identified SSX2IP and PASD1, as well as SSX2IP’s interacting partner, SSX2, as potential targets for the immunotherapy of myeloid leukemia." (PMID 29423088, 2018).
diffuse large B-cell lymphoma (2 papers, 2004 to 2015). "Here we report that the OX-TES-1 SEREX antigen, which showed immunological reactivity with serum from four out of 10 diffuse large B-cell lymphoma (DLBCL) patients, is encoded by a novel gene, PAS domain containing 1 (PASD1)." (PMID 15162151, 2004).
leukaemia (2 papers, 2007 to 2015). "The fact that four patients who had PASD1 specific T cell populations also had PASD1 expression in their leukaemia cells suggests the LAA specific-T cells are present in the periphery but are not effectively killing PASD1+ tumour cells." (PMID 26492414, 2015). "In the three patients who had PASD1 protein expression in their peripheral blood/leukaemia cells this concurred with the presence of PASD1-specific CD8+ T cells in the periphery as detected by the pMHC array." (PMID 26492414, 2015). "We have developed the pMHC array to detect CD8+ T-cell populations in leukaemia patients that recognise epitopes within viral antigens (cytomegalovirus (CMV) and influenza (Flu)) and leukaemia antigens (including Per Arnt Sim domain 1 (PASD1), MelanA, Wilms’ Tumour (WT1) and tyrosinase)." (PMID 26492414, 2015). "In addition these studies identified known leukemia antigens such as RHAMM, MAGE-A1 as well as novel targets for leukemia immunotherapy such as PASD1, SSX2IP and BAGE." (PMID 19662193, 2007).
lymphoma (2 papers, 2004 to 2022). A malignant (clonal) proliferation of B- lymphocytes or T- lymphocytes which involves the lymph nodes, bone marrow and/or extranodal sites. "Similar findings were also observed in the PASD1 expression study in lymphoma particularly the DLBCL patients." (PMID 37529004, 2022). "PASD1 has potential for lymphoma vaccine development that may also be widely applicable to other tumour types." (PMID 15162151, 2004).
melanoma (2 papers, 2004 to 2020). A malignant, usually aggressive tumor composed of atypical, neoplastic melanocytes. "PASD1 expression was also seen in the human cancer cell lines (Row P), with the melanoma (P5) and colorectal adenocarcinoma (P8) cell lines showing the highest expression levels." (PMID 15162151, 2004). "Levels of expression of GAGE, NY-ESO1, MAGEA1, PASD1, PRAME in melanoma cell lines were significantly higher than in STBS group (adj." (PMID 32042403, 2020). "Meanwhile, profiles of expression of HAGE, PASD1, SEMG1, SLLP1, SPANXA1, SSX1 weren’t significantly different in STBS and melanoma cell cultures at the complex assessment." (PMID 32042403, 2020).
colorectal cancer (1 paper, 2022). A primary or metastatic malignant neoplasm that affects the colon or rectum. "This study aims to validate PASD1 expression as a potential target for colorectal cancer immunotherapy by investigating its expression, immunogenicity of PASD1 peptide in inducing CD4 T cell immune response, cytotoxicity and cytokine expression." (PMID 37529004, 2022).
colorectal polyps (1 paper, 2022). "Such peptides could then be included in a CRC vaccine immunotherapy as well as colorectal polyps expressing PASD1." (PMID 37529004, 2022). "To date, this is the first study describing the CD4 T cell response towards PASD1 peptides in CRC and colorectal polyps patients." (PMID 37529004, 2022).
follicular lymphoma (1 paper, 2004). Follicular lymphoma is a form of non-Hodgkin lymphoma characterized by a proliferation of B cells whose nodular structure of follicular architecture is preserved. "Three of these patients had DLBCL transformation from follicular lymphoma, which generally has a poor prognosis; one of these patients showed a humoral immune response to the PASD1 protein." (PMID 15162151, 2004).
hyperplastic polyp (1 paper, 2022). A polyp found mainly in the stomach and colon. "Interestingly, all of the polyps samples that showed CD4 T cell response against PASD1 peptides were from hyperplastic polyps, a type of polyps with less association with cancer development." (PMID 37529004, 2022). "Interestingly, PASD1 mRNA expression was observed in many of the hyperplastic polyps samples instead of tubulovillous or tubular adenoma type." (PMID 37529004, 2022).
osteosarcoma (1 paper, 2020). A usually aggressive malignant bone-forming mesenchymal neoplasm, predominantly affecting adolescents and young adults. "Osteosarcoma was characterized by the presence of GAGE (40% 2/5), MAGEA1 (60% 3/5), PRAME (40% 2/5), NY-ESO1 (40% 2/5), PASD1 (60% 3/5), SLLP1 (60% 3/5), SSX1 (80% 4/5)." (PMID 32042403, 2020).
rectosigmoid tumors (1 paper, 2022). "The demographic data suggest that Chinese female patients more than 60 years old, diagnosed with late-stage rectosigmoid tumors may benefit from the PASD1 peptide immunotherapy approach." (PMID 37529004, 2022).
small intestine cancer (1 paper, 2004). A primary or metastatic malignant neoplasm involving the small intestine. "However, the PASD1 expression levels seen in the histologically-normal tissues from patients with uterus, lung and small intestine cancer may indicate that PASD1 expression is an early event in carcinogenesis occurring before histological changes are apparent." (PMID 15162151, 2004).
cancer (6 papers, 2004 to 2022). A tumor composed of atypical neoplastic, often pleomorphic cells that invade other tissues. "PASD1 is a cancer-associated antigen that can stimulate autologous T-cell responses, and it is therefore considered to be a potential immunotherapeutic target for the treatment of various hematopoietic malignancies." (PMID 35664317, 2022). "This shows that PASD1 might have a role in carcinogenesis and a potential subtyping marker in recognizing high-risk cancer." (PMID 37529004, 2022). "In conclusion, we have identified a novel CTA, PASD1, that warrants further study since its expression in both haematopoietic and nonhaematopoietic malignancies raises the possibility that this antigen may have a diagnostic or therapeutic use in a variety of cancers." (PMID 15162151, 2004). "This similarity implies that the dysfunction of circadian clock in male germ cells and cancer cells may be attributed to regulation by certain CTAs, which is supported by recent finding that a cancer/testis antigen PASD1 can suppress the circadian clock." (PMID 28903391, 2017). "Both PASD1 and SSX2 are CTAs that are expressed in cancer cells and immunologically protected sites." (PMID 29423088, 2018). "Our studies of the combined expression of PASD1_v1 and PASD1_v2 mRNAs point towards PASD1 being a novel CTA, showing somatic tissue expression restricted to normal testis while also showing widespread expression in cancer patients." (PMID 15162151, 2004). "Per ARNT Sim domain containing 1 (PASD1) is a cancer-testis antigen expressed in cancers including CRC but not in normal tissues except for normal testes." (PMID 37529004, 2022). "We are, however, currently unable to explain why, for example, the uterine tissue from cancer patients should show PASD1 expression, while the tumour tissue does not, although one difference could be the cellular composition of normal and malignant tissue." (PMID 15162151, 2004).
tumor (6 papers, 2004 to 2022). "The lack of expression in other patient samples, despite the presence of PASD1-specific T cells in the periphery suggests that these samples had not attracted PASD1-specific T cells from the periphery to the tumour or the T cells had already killed the PASD1 expressing tumour cells." (PMID 26492414, 2015). "There was a positive correlation between the source of the cell line (primary tumor or metastasis) and the expression of NY-ESO1 and PASD1 genes." (PMID 32042403, 2020). "PASD1 is one of the most frequently expressed tumour antigens in AML and PASD1 epitopes have been found to be recognised by T cells from AML patients (and this study)." (PMID 26492414, 2015). "Other cases have been reported, including a case of a man with brain metastases and nodal metastases who had a CR to concurrent treatment with ipilimumab and SRS and developed antibodies to the tumor antigens MAGEA3 and PASD1." (PMID 24403263, 2013). "Of these, only the C5 sample showed significant lysis of PASD1-positive SW480 tumor cell lines but not in the PASD1-negative HCT116 cell line, normal healthy sample and irCD4." (PMID 37529004, 2022). "Of note was the predominance of PASD1-specific T-cell responses in 8 of 26 AML patients, perhaps reflecting the presence of four HLA-A2 restricted pMHC-PASD1 on the array, rather than the single pMHC-epitopes detecting most other tumour antigens." (PMID 26492414, 2015). "Immunophenotyping studies of de novo DLBCL patients' tumours with antibodies to CD10, BCL-6 and MUM1 indicated that two patients mounting an immune response to PASD1 were of a poor prognosis non-germinal centre subtype." (PMID 15162151, 2004).
PASD1 also shares sentences with these, for which no sentence is quoted: breast carcinoma (1 paper); chronic myeloid leukaemia (1); colorectal adenocarcinoma (1); tubular adenoma (1); Wilms’ Tumour (1).